NGF (nerve growth factor)
Diseases named in the same sentence as NGF in open-access papers (continued):
Sharing a sentence is not in itself a finding about the gene and the disease.
adenomyosis (6 papers, 2011 to 2025). The growth of endometrial tissue inside the muscular wall of the uterine corpus. "It has been shown that dienogest can reduce the expression of nerve growth factor (NGF) and the density of nerve fibers associated with adenomyosis, as well as inhibit the secretion of inflammatory factor IL-8 by endometriotic stromal cells." (PMID 40223114, 2025). "At the same time, the increased levels of NGF and its receptors were noted to be associated with the inflammation status and augmented innervation in the uterine adenomyosis." (PMID 32676925, 2021). "The expression level of NGF was found to be associated with the severity of adenomyosis." (PMID 32676925, 2021). "In this study, we established a mouse model of adenomyosis and administrated NGF-neutralizing antibody into mice." (PMID 32676925, 2021). "There were 4242 peptides identified, of which 119 proteins were changed in the adenomyosis group compared with the control group, and 126 proteins were differentially expressed in the anti-NGF group compared with the adenomyosis group." (PMID 32676925, 2021). "In the present study, we established a mouse model of adenomyosis and explored the effects of anti-NGF therapy on the endometrial receptivity." (PMID 32676925, 2021). "With further studying clusters 3 and 5, we found those decreased proteins in adenomyosis, while those proteins were successfully recovered by anti-NGF treatment." (PMID 32676925, 2021). "Anti-NGF therapy was proved to improve fertility of mice with experimentally induced adenomyosis, possibly through promoting integrin-related proteins." (PMID 32676925, 2021). "The results of MS analysis demonstrated that 119 proteins were changed in the adenomyosis group compared with control group, and 126 proteins were differentially expressed in the anti-NGF group compared with the adenomyosis group (fold change > 1.5, P < 0.05." (PMID 32676925, 2021). "Our findings suggested that intervention of adenomyosis-related inflammatory response by the NGF-neutralizing antibody is beneficial to improve endometrial receptivity." (PMID 32676925, 2021). "The present study aimed to explore the effect of anti-NGF on the expression of proteins in uteri of mice-induced adenomyosis and assessed its potential role in improving pregnancy rate." (PMID 32676925, 2021). "After performing cluster analysis using Mfuzz package, we found that a group of proteins participated in cell-cell adhesion and metabolic processes, which were attenuated in the adenomyosis group, while those were successfully recovered by anti-NGF treatment." (PMID 32676925, 2021). "The pregnancy rates were 50%, 20%, and 30% in control, adenomyosis, and anti-NGF groups, respectively(n = 10, P > 0.05)." (PMID 32676925, 2021). "Results of MS functional enrichment analyses showed that a group of proteins participated in cell-cell adhesion and metabolic processes, and changed in adenomyosis group, while were successfully recovered by anti-NGF treatment." (PMID 32676925, 2021). "The expression levels of ITGA1, ITGB1, LAMC1, and CKM are downregulated in the adenomyosis group compared with those in control group, while those proteins are successfully recovered by anti-NGF treatment." (PMID 32676925, 2021). "It was revealed that anti-NGF treatment slightly enhanced the embryo implantation rate in mice with adenomyosis." (PMID 32676925, 2021). "Our results revealed that anti-NGF therapy can improve fertility of mice with experimentally induced adenomyosis, possibly through promoting integrin-related proteins." (PMID 32676925, 2021). "Our results also suggest the possibility of anti-NGF therapy for curing adenomyosis pain; however, further study is required to determine this issue." (PMID 21385399, 2011). "A mouse model with progressively worsening adenomyosis was generated to study the relationship between the expression of NGF and the severity of adenomyosis." (PMID 21385399, 2011).
adenomyosis (continued). "Discovered over 50 years ago, NGF has been extensively studied in various biological systems in an attempt to understand its role in adenomyosis." (PMID 21385399, 2011). "The protein levels of NGF (13 kDa) and its precursors (proNGF, 27 kDa), p75NTR (75 kDa) and trkA (145 kDa), in the uteri of adenomyosis and control mice were detected by western bolts." (PMID 21385399, 2011). "NGF, pro NGF, p75NTR and trkA levels increased in the uteri of adenomyosis mice as age increased (190 ± 5 d and 240 ± 5 d, P < 0.05, compared with 90 ± 5 d) and remained unchanged in controls." (PMID 21385399, 2011). "We examined the abnormal increase of NGF and its receptors in uteri of adenomyosis mice by western blot." (PMID 21385399, 2011). "The expressions of NGF, its precursors and receptors of adenomyosis mice were higher than those in controls in the 190 ± 5 and 240 ± 5 d age groups (P < 0.05)." (PMID 21385399, 2011). "In addition, the level of CKM was decreased in adenomyosis group, while that was increased in anti-NGF group." (PMID 32676925, 2021). "Embryo implantation rate in the adenomyosis group was significantly decreased compared with that in the control group (2.31% vs. 26.15%, P < 0.001) and anti-NGF treatment slightly enhanced the embryo implantation rate in mice with experimentally induced adenomyosis (9.23% vs. 2.31%, P = 0.017)." (PMID 32676925, 2021). "In the current study, we noted a crucial role of CKM during onset and recovery of adenomyosis, which indicated that anti-NGF treatment could improve the energy metabolism of uterine adenomyosis in mice." (PMID 32676925, 2021). "To examine this hypothesis, we established a mouse model of adenomyosis, with administration of the NGF-neutralizing antibody." (PMID 32676925, 2021). "In addition, the level of CKM was decreased in adenomyosis group whereas increased in anti-NGF group." (PMID 32676925, 2021). "In the present study, we found that integrin subunit α1 (ITGA1) and integrin subunit β1 (ITGB1) were decreased in adenomyosis group, while were elevated in Anti-NGF group, which might be beneficial for the embryo implantation." (PMID 32676925, 2021). "Western blotting confirmed that the expression levels of integrin alpha-1 (ITGA1), integrin beta-1 (ITGB1), laminin subunit gamma-1 (LAMC1), and creatine kinase M-type (CKM) were decreased in adenomyosis group, whereas those levels were elevated after anti-NGF treatment." (PMID 32676925, 2021). "In the present study, the low expression levels of PPP1R12C and PPP1R12B were partly related to the myometrium injury in adenomyosis, and anti-NGF therapy might be advantageous for repair of myometrial defect." (PMID 32676925, 2021). "Since NGF has abnormal expression in adenomyosis and has multiple effects on innervation, immunoregulation, cell proliferation and production of pain, it might be involved in the pathomechanism of adenomyosis." (PMID 21385399, 2011). "If NGF plays a role in adenomyosis, NGF levels and/or its receptors might change with the progress of this disease." (PMID 21385399, 2011). "For adenomyosis, which also has an increased density of nerve fibers in the uterus of symptomatic patients, NGF might have the contribution to this abnormal innervation." (PMID 21385399, 2011). "The reason for the increase in NGF and its receptors in adenomyosis mice is unclear." (PMID 21385399, 2011). "So the increase of endometrial glandular and stromal in adenomyosis might affect the expression of NGF and receptors, too." (PMID 21385399, 2011). "Therefore we speculate that this ever-increasing NGF effect in severe adenomyosis might contribute to the aggressive pain accompanied by this disease." (PMID 21385399, 2011). "Therefore, it is possible that NGF might be one of the important factors that participate in the pathological mechanism of adenomyosis." (PMID 21385399, 2011). "Therefore, NGF can be used as an indicator for the severity of adenomyosis." (PMID 21385399, 2011).
adenomyosis (continued). "This study aimed to investigate the expression of NGF and its two receptors in uteri and dorsal root ganglia (DRG) in an adenomyosis mouse model, as well as their relationship with the severity of adenomyosis." (PMID 21385399, 2011). "The protein levels of NGF and its receptors in uteri and trkA mRNA levels in DRG were higher in adenomyosis mice compared with those in controls, and these levels increased with the severity of disease." (PMID 21385399, 2011). "In this study, we investigated the expression of NGF and its receptors (p75NTR and trkA) in the uterus and DRG of mice with adenomyosis." (PMID 21385399, 2011). "In the present study, we evaluated the expression of NGF, p75NTR and trkA in uteri and DRG of adenomyosis mice." (PMID 21385399, 2011). "By examining the protein and mRNA levels of NGF and its receptors in the uterus and dorsal root ganglia (DRG) at different ages in adenomyosis mice, we aimed to evaluate any changes with the severity of adenomyosis in peripheral organs and the central nerve system." (PMID 21385399, 2011). "Consequently, the excessive generation of NGF in the lesion and the binding of NTRK2 in stromal cells may be connected to the activation of PI3K/AKT in endometrial stromal cells during adenomyosis." (PMID 39886033, 2024).
airway hyperresponsiveness (6 papers, 2006 to 2023). "In a subsequent study in the same experimental model, resveratrol-induced suppression of persistent airway inflammation and airway hyperresponsiveness was detectable 60 days after RSV infection and was associated with decreased levels of BALF nerve growth factor (NGF)." (PMID 34093569, 2021). "As increased NGF in the BALF of asthmatic patients induces smooth muscle hyperplasia in the airway and anti-NGF antibodies improve airway hyperresponsiveness, NGF is also considered a therapeutic target for lung disease." (PMID 36769060, 2023). "Nicotine has been shown to activate the α7 nAChR signaling pathway in lung fibroblasts to induce NFκB transcriptional activity/nuclear translocation and produce nerve growth factor (NGF) in smokers, which contributes to airway hyperresponsiveness." (PMID 34069141, 2021). "The neurotrophins, including nerve growth factor (NGF), brain-derived neurotrophic factor (BDNF) and neurotrophin-3 (NT-3), have been shown to be elevated during airway inflammation and evoke airway hyperresponsiveness." (PMID 16441896, 2006).
alcohol (6 papers, 2018 to 2025). "Several studies have shown that alcohol dependence is associated with alterations in plasma levels of NGF and after alcohol withdrawal a rapid increase in the serum NGF concentration was observed." (PMID 40114019, 2025). "In particular, voluntary wheel running increases neurotrophins, both BDNF and NGF, and NGF has been shown to be responsible for exercise-induced rescue of the cholinergic phenotype following alcohol-related brain damage." (PMID 39436939, 2024). "Lee33 found that plasma BDNF and NGF levels were higher in patients with alcohol dependence than in the healthy subjects." (PMID 29520063, 2018). "NGF and BDNF are peptides that not only play a pivotal role in the development, survival, and function of the central and peripheral nervous systems but also regulate the pathogenesis of other problems induced by alcohol exposure." (PMID 38539304, 2024).
autism (6 papers, 2016 to 2023). Persistent deficits in social interaction and communication and interaction as well as a markedly restricted repertoire of activity and interest as well as repetitive patterns of behavior. "Recent studies have implicated NGF signaling in autism core behavioral deficits." (PMID 31827489, 2019). "Our experimental results show that plasma NGF levels in children with autism (arithmetic mean = 23.25) are approximately 50% higher than those in TDC (arithmetic mean = 15.98)." (PMID 36233217, 2022). "Another study on differential alternative splicing in the blood samples from 2- to 4-year-old boys with autism showed a significant difference for several NGF signaling genes including NGF receptor." (PMID 31827489, 2019). "Genetic analyses of heritable quantitative traits that correlate with autism identified an association of NGF locus with nonverbal communication in a large cohort of patients." (PMID 31827489, 2019).
bladder disorder (6 papers, 2012 to 2023). "Taken together, increased serum and urinary NGF levels in patients with OAB refractory to antimuscarinic treatment suggest these bladder disorders could be caused by chronic inflammation." (PMID 24098552, 2013). "The presence of increased serum and urinary NGF levels in patients with IC/BPS suggests that this bladder disorder might be caused by chronic inflammation." (PMID 23028581, 2012). "Increased distribution of NGF or NGFR p 75 in the urothelium is more often reported in painful bladder disorders, whereas higher levels of NGF or NGFR p75 have been described for the submucosal tissue and detrusor in functional bladder alterations." (PMID 33692976, 2021). "Only a few studies have immunohistochemically evaluated NGF or its low-affinity receptor p75 in bladder wall biopsies of patients with painful or irritative bladder disorders." (PMID 33692976, 2021). "The level of NGF was statistical significantly higher in the groups with bladder disorders than in the control group consisting of four women with stress incontinence without any irritative symptoms." (PMID 33692976, 2021). "Recent investigations into the pathophysiology of BPS/IC have demonstrated elevated levels of several bladder and urinary biomarkers in this bladder disorder, such as nerve growth factor (NGF)." (PMID 27462520, 2016). "Recent investigations into the pathophysiology of IC/BPS have demonstrated elevated levels of several bladder and urinary biomarkers in this bladder disorder, such as nerve growth factor (NGF)." (PMID 23028581, 2012). "Increased urinary NGF levels in IC/BPS patients suggest that chronic inflammation is involved in this bladder disorder." (PMID 23028581, 2012). "Similar to other painful bladder disorders, pain transmission in BE after intitial closure may in part be facilitated by elevated NGF signaling through its receptor." (PMID 33692976, 2021). "NGF seems to be key factor in painful and functional bladder disorders." (PMID 33692976, 2021). "The nerve growth factor (NGF) is regarded as a marker for pain in different bladder disorders." (PMID 33692976, 2021). "When DO, IC/BPS, and DV were grouped as pathological bladder diseases, 8-isoprostane, TAC, 8-OHdG, VEGF, NGF, and PGE2 were significantly higher, though IL-2 was significantly lower than in those with HSB, and the controls." (PMID 36983336, 2023). "There are still many unresolved issues concerning the role of NGF and its receptor NGFR p75 in the pathophysiology of bladder disorders." (PMID 33692976, 2021). "In our study, serum NGF and CRP levels were significantly increased in IC/BPS patients, suggesting that chronic inflammation is involved in this bladder disorder." (PMID 24146927, 2013).
Brain atrophy (6 papers, 2016 to 2023). Partial or complete wasting (loss) of brain tissue that was once present. "In patients with systemic lupus erythematosus with neuropsychiatric manifestation, immune cell NGF levels were found to be correlated with brain atrophy reflected by lateral ventricle enlargement and thalamic volume loss." (PMID 31105606, 2019). "We found no significant positive effect on BV by MRI, while results derived from previous dose cohorts showed a slower rate of brain atrophy by MRI in a subset of patients during NGF administration." (PMID 27389402, 2016). "The NGF treatment modifies the trajectories of global brain atrophy and CSF biomarkers." (PMID 32375872, 2020). "First, while NGF might indeed lead to decreased efficiency of neural networks, this does not have to manifest necessarily in brain atrophy detectable by MRI." (PMID 31105606, 2019).
experimental autoimmune encephalomyelitis (6 papers, 2008 to 2024). An autoimmune demyelinating disease of the central nervous system that is produced experimentally in animals by the injection of homogenized brain or spinal cord in Freund's adjuvant. "To address this urgent need, we sought to determine the therapeutic efficacy of the adipose-derived MSCs (ADMSCs) and ADMSC-derived MVs (ADMSC-MVs) expressing NGF in mice with an experimental autoimmune encephalomyelitis (EAE), a model of MS." (PMID 37176039, 2023). "Osthole further blocked the reduction of NGF levels in experimental autoimmune encephalomyelitis mice." (PMID 32403381, 2020).
Granuloma (6 papers, 2010 to 2025). A compact, organized collection of mature mononuclear phagocytes, which may be but is not necessarily accompanied by accessory features such as necrosis. "In mice, the eggs of Schistosoma mansoni can cause granulomas and elevate levels of NGF in the central nervous system and liver." (PMID 39795948, 2024). "The authors suggested that the neuropathological dysfunctions in neuroschistosomiasis may be linked to changes in the NGF levels caused by local formation of granulomas." (PMID 35563321, 2022). "We found that granuloma-induced mechanical allodynia was associated with increased expression of the pro-inflammatory markers TNF-α, NGF and COX-2 in the DRGs." (PMID 21219627, 2011). "Sarcoid granulomas in the mediastinal lymph node also showed positive immunoreactivity for NGF, BDNF, NT-3, TrkA, TrkB and TrkC, localized to the granulomas and the surrounding lymphoid tissue." (PMID 21059230, 2010). "BALF concentrations of NGF and neurotrophin-3 (NT-3) were significantly increased, and immunoreactivity against NGF, BDNF, NT-3, and tyrosine protein kinase receptors (TrkA, TrkB, and TrkC) in granulomas was found in patients with sarcoidosis using immunohistochemical analysis." (PMID 40361957, 2025). "No or less immunoreactivity for NGF, BDNF or NT-3 was found within fibrotic tissue around granulomas." (PMID 21059230, 2010).
Hydrocephalus (6 papers, 2005 to 2024). Hydrocephalus is an active distension of the ventricular system of the brain resulting from inadequate passage of CSF from its point of production within the cerebral ventricles to its point of absorption into the systemic circulation. "NGF and other neurotrophins and their receptors are upregulated in brain damage including that caused by hydrocephalus." (PMID 15953386, 2005). "Increased NGF mRNA levels have been detected in the medial septal nucleus, striatum and corpus callosum in experimentally-induced hydrocephalus in rats." (PMID 17020616, 2006). "Increased levels of NGF when compared to controls have been verified in another study of 16 children with communicating hydrocephalus." (PMID 17020616, 2006). "They found that the expression level of NGF increased with the severity of hydrocephalus symptoms." (PMID 38337135, 2024). "They measured the levels of NGF in nine adult patients with high pressure hydrocephalus (the authors define high pressure as CSF pressure >10 cm H20) and seven patients with ex-vacuo hydrocephalus." (PMID 17020616, 2006). "Furthermore, hydrocephalic H-Tx rats have alterations in brain NGF concentrations and children with hydrocephalus have elevated NGF in the CSF." (PMID 15953386, 2005).